LCN2 (lipocalin 2)
Diseases named in the same sentence as LCN2 in open-access papers (continued):
Sharing a sentence is not in itself a finding about the gene and the disease.
colorectal cancer (continued). "High expression of PROM1, LEMD1, CLDN2, PIGR and LCN2 were associated with CRC cell migration, promoting colorectal cancer growth and metastasis." (PMID 36816926, 2023). "Here, we explored the functional role and mechanisms of LCN2 in tumorigenesis using murine colitis-associated cancer (CAC) models and human colorectal cancer (CRC) cells." (PMID 35470375, 2022). "According to one publication, after the transduction of this gene in BMSCs, Lcn2 was overexpressed and intravenous injection of BMSCs/Lcn2 in the mouse model of colorectal cancer led to a reduction in liver metastasis and expression of VEGF in liver tissue." (PMID 34249257, 2021). "An integrative analysis identified colorectal cancer-related genes, including LCN2 and DUOX2, for which gene expression is correlated with the abundance of colorectal cancer-associated bacteria, such as Ruminococcaceae and Veillonella." (PMID 31992345, 2020). "For example, downregulated miR-138 contributed to overexpressed LCN2 in colorectal cancer with liver metastasis." (PMID 31485266, 2019). "LCN2 expression in colorectal cancer was detected by immunohistochemistry in 400 tissue specimens and Kaplan-Meier survival analysis was performed." (PMID 27912767, 2016). "In addition, the promoter activity of NF-κB is antagonized by LCN2, which suppresses the metastasis of colorectal cancer through the snail signalling pathway." (PMID 40109857, 2025). "In contrast, studies have shown that LCN2 plays a tumor-suppressive role in colorectal cancer." (PMID 40109857, 2025). "LCN2 suppresses ferroptosis via dual mechanisms—iron metabolism regulation and antioxidant gene expression—thereby driving chemoresistance and tumor progression in colorectal cancer." (PMID 40313933, 2025). "TFF3, TFF1, SELE, AHCY, LCN2, CEACAM5, and RETN are consistently upregulated across a variety of datasets and analyzes, which supports their crucial roles in the underlying mechanisms of colorectal cancer progression." (PMID 39839775, 2024). "Another study showed that overexpression of LCN2 induce tumor apoptosis of colorectal cancer." (PMID 38035773, 2024). "Compared to healthy cells, in colorectal cancer cells levels of Lipocalin 2 (LCN2) are elevated." (PMID 39839775, 2024). "•LCN2 was significantly increased in tumor-infiltrating T cells of colorectal cancer." (PMID 38072118, 2023). "Lcn2 is also known to be overexpressed in human colorectal cancer (CRC) and other cancers." (PMID 33598162, 2021). "Thus, combining therapeutics targeting LCN2 and c-Src in invasive tumors might result in better patient outcomes and improved responses to chemotherapy in colorectal cancer." (PMID 40356520, 2025). "In addition, a xenograft model showed that LCN2 promotes the progression of colorectal cancer." (PMID 40109857, 2025). "However, paradoxical roles of LCN2 have been reported in colorectal cancer." (PMID 40109857, 2025). "Therefore, the role of LCN2 in the progression of colorectal carcinoma could depend on bacterial strains present in the gut." (PMID 40109857, 2025). "In addition, patients with colorectal cancer had a higher abundance of Enterobacteriaceae compared with healthy controls as determined by CFU counts (controls: 47 ± 20 vs. colorectal cancer: 104 ± 37 CFUs, P < 0.028), and fecal Lcn-2 levels positively correlated with Enterobacteriaceae abundance." (PMID 38934090, 2024). "In the regulatory effect of lipocalin 2, ITGB3 conferred resistance to 5-fluorouracil in colorectal cancer." (PMID 38814534, 2024). "Nevertheless, baseline serum levels of LCN2 and MMP9 (as determined by the ELISA measurements) in 24 cases were similar to previously reported values in patients with colorectal cancer and considerably higher than those in healthy subjects." (PMID 27461255, 2016).
colorectal cancer (continued). "With the increase in pathological grading, staining intensities of LCN-2 and MMP-9 in neoplastic cells became stronger, and in high-grade intraepithelial LSTs expression was greater than in TNM stage I colorectal carcinomas." (PMID 27339395, 2016). "Oncogenic and tumor-suppressive roles of LCN2 have been reported in different types of tumors, regardless of the contradictory roles reported in colorectal cancer." (PMID 40109857, 2025). "Seven proteins namely TFF3, LCN2, CEACAM5, TFF1, SELE, RETN, and AHCY proteins of both phases were found to be upregulated in colorectal cancer in human protein atlas database, also were significant in our UK Biobank dataset and had an essential function in CRC." (PMID 39839775, 2024). "LCN2 is involved in oncogenesis and progression in a variety of cancers and negatively modulated cell proliferation and epithelial-mesenchymal transition (EMT) by regulating energy metabolism-related gene expression in colorectal carcinoma." (PMID 39139502, 2024). "Furthermore, LCN2 was illustrated to be a vital regulator in EMT, invasion and metastasis of colorectal cancer, mainly manifested by its correlation with E-cadherin and β-catenin expression." (PMID 32076707, 2020). "However, neither mechanisms nor the role that LCN2 plays in the metastasis of colorectal cancer are clear." (PMID 27912767, 2016). "Furthermore, with the increase of pathological grading, the staining intensity of LCN-2 and MMP-9 in neoplastic cells of LSTs gradually increased, and LCN-2 and MMP-9 staining intensity in high-grade intraepithelial LSTs was more intense than in TNM stage I colorectal carcinomas, respectively." (PMID 27339395, 2016). "The specific sites of positive staining for LCN-2 and MMP-9 were cytoplasm in LSTs and TNM stage I colorectal carcinomas, whereas no staining or only faint staining was found in the normal control group." (PMID 27339395, 2016).
Cognitive impairment (51 papers, 2012 to 2026). Abnormal cognition is characterized by deficits in thinking, reasoning, or remembering. "Bilateral injection of recombinant LCN2 protein into the lateral ventricles induced hippocampal neuronal loss, synaptic and cognitive impairments, suggesting that LCN2 is implicated in the pathogenesis of SAE." (PMID 40025014, 2025). "Our previous studies report that upregulating systemic and hippocampal LCN2 levels causes cognitive deficits in HFD or ob/ob mice." (PMID 38201988, 2024). "Other studies have also implicated LCN2 in neurodegenerative and cognitive disorders displaying neuronal loss, alterations in astrocytes, neuroinflammatory responses, and synaptic and network dysfunction." (PMID 38991663, 2024). "Lcn2 deficiency successfully mitigated myelin phagocytosis by astrocytes and ameliorated demyelination and cognitive impairment." (PMID 35241660, 2022). "When the LCN2 concentration in the two biological fluids was considered together, the association between LCN2 concentration and cognitive impairment (MCI + AD) remained only for the CSF levels." (PMID 34248600, 2021). "This study aimed at investigating the association between LCN2 measured in serum and cerebrospinal fluid (CSF) with cognitive impairment." (PMID 34248600, 2021). "This explanatory study suggests that the association between serum and CSF LCN2 concentrations with cognitive impairment reported in the literature must be further analyzed for confounders." (PMID 34248600, 2021). "We report that J20 and Lcn2-deficient J20 (J20xLcn2 KO) mice at 12 months of age show equally severe AD-like behavioral changes, cognitive impairment, plaque formation, and glial activation." (PMID 30501637, 2018). "Notably, alterations in LCN2 concentrations in CSF have been linked to cognitive impairment, suggesting its potential as both a biomarker and a therapeutic target for neurological conditions." (PMID 41018204, 2025). "Together, these findings strongly support that LCN2 might play a significant role in the neuronal loss associated with LPS-related synaptic and cognitive impairments." (PMID 40025014, 2025). "We compared the photostimulation-induced cognitive impairment between Lcn2-deficient and WT mice." (PMID 38991663, 2024). "LCN2 has been linked to cognitive impairment, and increased LCN2 levels have been observed in patients and mouse model of AD, as well as in the postmortem brain of patients with mild cognitive impairment." (PMID 37362002, 2023). "Furthermore, in line with the lines of evidence revealing that elevated LCN2 levels are closely linked to memory deficits in diabetic mice or patients, increased hippocampal LCN2 expression is correlated with neuroinflammation and cognitive impairment." (PMID 35884685, 2022). "Further, LCN2 mediates hippocampal damage in a model of vascular dementia (VaD) and high CSF LCN2 levels were reported to be a promising diagnostic biomarker for VaD, whereas decreased levels of CSF LCN2 were found in patients with mild cognitive impairment (MCI) due to AD." (PMID 35027079, 2022). "Furthermore, mild cognitive impairment is associated with higher plasma LCN2 levels." (PMID 23272119, 2012). "Through the integration of transcriptomic analyses, clinical investigations, and molecular mechanism validation, we have demonstrated that LCN2 expression is significantly upregulated prior to the onset of cognitive impairment symptoms." (PMID 40365739, 2025). "Previous studies have shown that chronic exposure of the brain to Lcn2 can lead to neurofunctional dysregulation and cognitive impairment, while reducing Lcn2 expression can alleviate neuroinflammatory damage." (PMID 39110292, 2024). "Previous studies have suggested that plasma LCN2 is involved in the early inflammatory events of mild cognitive impairment (MCI) and Alzheimer ‘s disease (AD)." (PMID 37543589, 2023).
Cognitive impairment (continued). "On the other hand, LCN2 has also been described with important roles in the diseased brain, particularly in mild cognitive impairment, Alzheimer’s disease, multiple sclerosis and, more recently, in Parkinson’s disease." (PMID 37168715, 2023). "Clinical studies have confirmed an increased level of LCN2 in the serum of patients with mild cognitive impairment and in the cerebrospinal fluid of patients with multiple sclerosis." (PMID 36974345, 2023). "For instance, studies on humans indicated slightly elevated levels of LCN-2 in the plasma of patients with mild cognitive impairment and the local concentration of LCN-2 in the brain tissue of patients with multiple sclerosis." (PMID 35493318, 2022). "Our results are consistent with a previous study that reported that the circulating LCN2 levels in a cognitive impaired population were higher than a control group with normal cognition." (PMID 35302058, 2022). "Some previous studies reported unaltered or even slightly elevated plasma or serum LCN2 levels in patients with mild cognitive impairment (MCI) and preclinical AD." (PMID 35027079, 2022). "Lcn-2 has been shown to promote cell death and iron dysregulation, in addition to neuroinflammation, leading to cognitive impairments." (PMID 35912090, 2022). "LCN2 has been found to be decreased in cerebrospinal fluid (CSF) but elevated in plasma of patients with mild cognitive impairment and AD." (PMID 34179014, 2021). "A study using the J20 mouse model showed different results from this study in cognitive impairment and glial activation because a significant amount of amyloid plaque overwhelmed the effect of LCN2." (PMID 34829528, 2021). "Lipocalin 2 (LCN2), an iron-related protein, has been suggested as a potential marker for mild cognitive impairment (MCI) and AD." (PMID 34248600, 2021). "So, a future study should investigate LCN2 expression and cognitive impairment after intrahippocampal injection of LPS in order to clarify the role of LCN2." (PMID 34829528, 2021). "We also performed the EPM task to further determine cognitive impairment in lipocalin 2 injected mice." (PMID 34565419, 2021). "Previously, the same group reported increased plasma levels in patients with mild cognitive impairments, supporting the correlation between LCN2 and cognitive deficits." (PMID 33613327, 2021). "Next, we performed a binary logistic regression analysis for the outcome cognitive impairment (belonging to the MCI + AD group) considering as independent variables the LCN2 concentration in the serum and CSF, alone or together." (PMID 34248600, 2021). "In a vascular dementia model, astrocyte-derived LCN2 mediated cognitive impairment and hippocampal damage." (PMID 30871254, 2019). "Here we show that, under standard housing conditions, LCN2-null mice display anxious and depressive-like behaviors, as well as cognitive impairment in spatial learning tasks." (PMID 23908604, 2013). "Studies have shown that elevated plasma LCN2 levels are associated with non-motor symptoms in patients with Parkinson disease, and their mediated neuroinflammation is associated with cognitive impairment in patients with Parkinson disease." (PMID 41018204, 2025). "The role of LCN2 in postoperative cognitive impairment remains to be elucidated." (PMID 41018204, 2025). "Nonetheless, the utility of LCN2 as an early warning indicator for VCI in individuals with cerebrovascular risk factors but without cognitive impairment necessitates further longitudinal studies." (PMID 40365739, 2025). "Peripheral blood LCN2 levels are also elevated in patients with mild cognitive impairment." (PMID 41018204, 2025). "Interestingly, the recombinant LCN2 protein exhibited similar effects on synaptic dysfunction and cognitive deficits in C57 mice." (PMID 40025014, 2025).
Cognitive impairment (continued). "In the CNS, LCN2 is closely associated with altered brain homeostasis and specific regions affected in neurodegenerative diseases, including AD and MS, such as elevated levels of LCN2 in plasma and cerebrospinal fluid (CSF) in patients with mild cognitive impairment, depression, and MS." (PMID 41007258, 2025). "Mechanistic studies conducted using knockout animal models and hippocampal neuronal cultures showed that lipocalin-2 (LCN2), derived from reactive astrocytes, mediated neuroinflammation and induced cognitive impairment by decreasing the LTP through the reduction of neuronal NMDA receptors." (PMID 38991663, 2024). "Similarly, treatment with l-α-AA reduced the optogenetic stimulation-induced cognitive impairments as well as the Lcn2 and cytokine mRNA expression levels in the ChR2-eYFP group." (PMID 38991663, 2024). "Interestingly, LCN2 levels in serum and cerebrospinal fluid have been suggested as a potential marker for mild cognitive impairment and Alzheimer’s disease, suggesting a role of LCN2-mediated iron homeostasis in the brain." (PMID 37174093, 2023). "Studies have shown that blood levels of LCN2 protein increase with age and mild cognitive impairment in different diseases of the CNS, including Alzheimer’s disease, Parkinson’s disease and multiple sclerosis, and that brain tissue levels of LCN2 protein increase in people after death." (PMID 36671050, 2023). "Our findings suggest that LCN2 could have a predictive role as an early biomarker for cognitive impairment and changes in the prefrontal cortex related to executive function and in the left hippocampus related to verbal memory." (PMID 35302058, 2022). "Previously, individuals with cognitive impairment showed an elevated level of LCN2 in the plasma." (PMID 35281301, 2022). "Furthermore, a 5-year follow up in a random subpopulation was conducted to assess the predictive property of circulating LCN2 level on mild cognitive impairment by assessing cognitive performance and the anatomical structure of the brain and its volume." (PMID 35302058, 2022). "In addition, several clinical studies have been conducted in many cognitive impaired populations to explore the relationship between LCN2 and cognitive status." (PMID 35302058, 2022). "Collectively, our results suggest that lipocalin 2 overexpression in the brain may provoke cognitive impairment, including social avoidance and anxiety-like behaviors, similar to RSDS-treated mice." (PMID 34565419, 2021). "Clinical and MRI data from cohort 1 and 4 suggest that higher LCN2 levels are associated with the degree of cognitive impairment in VBI, but not in AD." (PMID 32001681, 2020). "Studies showed that Lcn2 protein levels in blood increase with age and mild cognitive impairment, and are increased in human post-mortem brain tissues in different diseases of the central nervous system (CNS), including AD, Parkinson’s disease, and multiple sclerosis." (PMID 30501637, 2018). "In addition, LCN2-null mice displayed anxious and depressive-like behaviors as well as cognitive impairment in spatial learning tasks, in accordance with the symptoms of morphine addiction." (PMID 25012590, 2014). "LCN2 is present in the active phases of multiple sclerosis in both rodent models and in humans, but decreased in the cerebrospinal fluid of individuals with mild cognitive impairment." (PMID 23908604, 2013). "This indicates that an increased LCN2 may induce cognitive impairments." (PMID 40025014, 2025). "The description of increased LCN2 plasma levels during mild-cognitive impairment, and the consequent suggestion that it might be helpful in predicting the progression of this state to Alzheimer’s disease, should be considered with caution in light of the present results." (PMID 37168715, 2023). "Thus, there is a possibility that LCN2 could be one of factors involved in the MetS condition, and may contribute to cognitive impairment." (PMID 35302058, 2022).
Cognitive impairment (continued). "Of note, while the present study strongly suggests that measuring LCN2 levels in biological fluids is not useful for diagnosis purposes, LCN2 may still be associated with the molecular mechanisms underlying cognitive impairment and/or AD." (PMID 34248600, 2021). "In particular, plasma LCN2 was found to be negatively corrected with clinical dementia rating scores and positively corrected with mini-mental status examination scores, and is therefore regarded as a potential marker to predict the progression from mild cognitive impairment to AD." (PMID 34179014, 2021). "At the molecular level, MASLD altered the expression of key hippocampal genes-including TCF7L2, LCN2, and AQP1-impacting immune response, lipid metabolism, and apoptotic pathways, which collectively contributed to cognitive deficits." (PMID 41674921, 2026). "In a rat model of VaD (bilateral common carotid artery stenosis (BCAS)), reactive astrocyte-derived lipocalin-2 (Lcn2) in the hippocampus has been shown to mediate BBB damage leading to neuroinflammation and cognitive impairment." (PMID 38300642, 2024). "Our study investigated the release of LCN2 from hippocampal CA1 astrocytes during optogenetic stimulation, revealing its involvement in cognitive impairment." (PMID 38991663, 2024). "This study shows that repetitive and sustained stimulation of hippocampal astrocytes induces reactive astrogliosis and subsequent LCN2 release, triggering neuroinflammation, inhibition of NMDA-receptor-related neuronal activity and cognitive impairment." (PMID 38991663, 2024). "Lcn2 did not significantly affect other AD-like characteristics (including behavioral changes, cognitive impairment, plaque load, and glial activation) in the J20 mouse model at 12 months of age." (PMID 30501637, 2018). "Of interest, decreased levels of CSF LCN2 were found in individuals with mild cognitive impairment, and mice lacking LCN2 presented cognitive impairment." (PMID 24148264, 2013). "However, a definitive link between LCN2, sustained neuroinflammation in the hippocampus, and cognitive impairment has not yet been established, and it remains unclear whether hippocampal inflammation persists along with chronic reactive astrocytosis." (PMID 38991663, 2024).